IL6 (interleukin 6)
Diseases named in the same sentence as IL6 in open-access papers (continued):
Sharing a sentence is not in itself a finding about the gene and the disease.
liver cancer (continued). "In liver cancer, the production of IL6 in response to the activation of TDO2-kynurenine-AHR signaling was also demonstrated to activate STAT3 and NF-κB/TIM4 signals to sustain cell proliferation, demonstrating additional protumoral properties of autocrine IL6 signaling pathways." (PMID 35681770, 2022). "Although the role of IL-6 in senescence-induced anti-tumour effects was reported in non-HCC, the role of IL6 in senescence-mediated anti-tumour effects in different types of liver cancers is still under investigation and seems to be dependent on the tumour type (E.G., personal communication)." (PMID 34047814, 2021). "Additionally, a methylation study of liver cancer indicated that low expression of IL-6 can reduce angiogenesis in HCC tissues, suggesting that the IL-6/STAT3 signaling pathway can promote angiogenesis in tumor tissues and provide nutrient guarantees for the development of tumorigenesis." (PMID 34976809, 2021). "Moreover, in liver cancer, a recent paper declared that certain lncRNAs could suppress liver CSC expansion via competitively binding the IL‐6 promoter and suppressing IL‐6 transcription to block NF‐kB‐mediated transcription." (PMID 33634982, 2021). "TM4SF5 interacts with IL6R, leading to STAT3 activation independent of IL6 in hepatic cancer cells." (PMID 34921636, 2021). "For example, hepatitis B virus (HBV) infection could induce the accumulation of mitochondrial reactive oxygen species (ROS), thereby inhibiting the expression of suppressor of cytokine signaling 3 (SOCS3) and activating the interleukin-6 (IL-6)/STAT3 pathway, ultimately leading to liver cancer." (PMID 32735635, 2020). "IL-6, STAT3, TNF-α and NF-κB are reported to play a central role in inflammation and control the expression of an array of growth factors and cytokines that may involve in hepatic cancer development." (PMID 27760163, 2016). "Our data demonstrate that in hepatic cancer cell lines APE1 redox function is involved in TNF-α and FA-induced IL-8- and IL-6 expression, and its inhibition by E3330 may represent a promising tool for reducing the early inflammatory process in liver diseases such as in NASH." (PMID 23967134, 2013). "As IL-6 plays an integral role in the development of hepatocyte inflammation, liver disease, and liver cancers, the utilization of the MAPK-ERK during HBV infection may highlight a potential role of this pathway facilitating the development of HCC and other liver cancers in vivo." (PMID 31336840, 2019). "Moreover, intravenous injection of rhBMP2 and implantation of rhBMP2 collagen gels in tumor-burdened mice could increase the IL6 levels in both peripheral blood and tumor tissues, indicating that MDSC expansion, induced by BMP2, enhanced liver cancer growth via IL6." (PMID 32195173, 2020). "Further, we confirmed that IL-6 and HGF secreted by H-CAFs but not by the liver cancer cells were crucial to EMT of HCC cells." (PMID 32792856, 2020). "Our results showed that Raloxifene inhibited STAT3 phosphorylation induced by IL-6, but not by LIF in Hep-3B liver cancer cells." (PMID 28430601, 2017). "Nevertheless, since we proved that IL-6-mediated upregulation of PLIN5 at the protein level is not limited to a specific liver cell line, we concluded that this is a newly discovered mechanism of PLIN5 regulation in hepatic cancer cells." (PMID 37108378, 2023). "Studies of miR-375 among liver cancers have demonstrated that this resistance may function through modulation of Non-SMC Condensin II Complex Subunit G2 (NCAPG2), Interleukin 6 (IL-6) and Transforming growth factor-beta (TGF-β)." (PMID 36674758, 2023). "In the intensive investigations on the role of the IL-6/STAT3 pathway, although unfolded many mechanistic understandings related to the development of liver cancer and other malignancies, no single drug was yet approved that is based on these mechanistic findings." (PMID 34047814, 2021).
liver cancer (continued). "Agents expected to enhance the self-renewal of liver cancer stem cells, EGF/FGFβ/B27 and Il-6, induced oscillations in [Ca2+]cyt in Hep12 cells, but not in Hep-11 cells, suggesting that oscillations in [Ca2+]cyt are an important characteristic of liver cancer stem cells." (PMID 32987945, 2020). "In liver cancer stem cells, Shh/Gli‐regulated cell functions were also found to be mediated by activation of the IL‐6/STAT3 pathway, but whether there is a similar direct effect of Shh‐blockade on IL‐6‐mediated STAT3 signaling was not reported." (PMID 34482626, 2022). "In an inflammation-induced liver cancer mouse model, single-cell RNA sequencing analysis (scRNA-seq) revealed that HCC-CCA may originate from hepatic progenitor cells, whose transformation depends on IL-6 secreted by parenchymal and non-parenchymal liver senescent cells via the IL-6-gp130 pathway." (PMID 38275386, 2023).
respiratory failure (224 papers, 2011 to 2026). The significant impairment of gas exchange within the lungs resulting in hypoxia, hypercarbia, or both, to the extent that organ tissue perfusion is severely compromised. "Interleukin-6 (IL-6) has been reported to be a marker associated with respiratory failure in COVID-19 pneumonia, with higher IL-6 levels observed in critically ill and deceased patients." (PMID 40431655, 2025). "This aligns with the established role of IL-6 as a key predictor of the need for mechanical ventilation, as indicated by its strong association with respiratory failure and intubation." (PMID 39203987, 2024). "Theoretically, PMX adsorbs inflammatory mediators, such as high mobility group box 1, neutrophils and interleukin-6 that cause respiratory failure in AE-IPF." (PMID 37821999, 2023). "Early detection of IL-6 concentrations can facilitate the timely stratification of patients at risk of acute respiratory failure." (PMID 37214473, 2023). "In CAP patients, elevated serum IL-6 concentrations during hospitalization are associated with higher rates of respiratory failure and mortality." (PMID 37214473, 2023). "Multivariate regression analysis showed that serum IFN-α levels higher than the cut-off value of 107 pg/mL showed the highest OR for hypoxemic respiratory failure, demonstrating a greater than two-fold stronger association as compared with IL-6 and CXCL10." (PMID 37731495, 2023). "In contrast, among patients who did receive IL-6 inhibitors, males were at lower risk of progression to respiratory failure or death compared to females (HR = 0.65; CI (0.32–1.33))." (PMID 37598275, 2023). "In COVID-19 infection, an increased serum level of IL-6 has been found to be associated with the severity of disease, including the risk of respiratory failure and death." (PMID 36829456, 2023). "CRS seems to be associated with IL-6 dysregulation, elevated IL-6 levels being associated with respiratory failure and poor prognosis." (PMID 37969879, 2023). "Decreased serum IL-6 concentration within 24 h after admission indicated a lower risk of developing respiratory failure in the later admission course (Receiver Operating Characteristic [ROC] curve = 0.696)." (PMID 37214473, 2023). "Those who are severely impacted and at high risk for respiratory failure have been found to present high levels of serum cytokines, such as interleukin-6 (IL-6)." (PMID 35242747, 2022). "Increased serum interleukin 6 (IL-6) concentrations, which have been associated with respiratory failure and ARDS, can also occur." (PMID 36532785, 2022). "The occurrence of macrophage activation syndrome and poor antigen presentation, caused by interleukin 6 (IL-6), are predisposing factors for severe respiratory failure." (PMID 34944639, 2021). "Lipid metabolism in the lungs is associated with chronic respiratory failure, airway obstruction, bronchoconstriction, IL-6 generation, vascular permeability, airway remodeling, mucus secretion, and inflammation in COPD." (PMID 34055821, 2021). "The result indicated that leptospiremia, pNGAL, and IL-6 levels at baseline (day 1) were associated with severe coagulopathy, severe cardiovascular system failure, pulmonary hemorrhage, and severe respiratory failure." (PMID 34272435, 2021). "The study of IL-6 in patients with severe COVID-19 pneumonia revealed its high association with outcomes, such as, death and respiratory failure." (PMID 35054223, 2021). "Data from non‐pregnant women demonstrate a strong association among elevated IL‐6 levels, risk of respiratory failure, and the subsequent need for mechanical ventilation." (PMID 32816307, 2020). "Elevated levels of IL‐6 were found in more than half of the sick patients and are associated with respiratory failure and mortality." (PMID 33304584, 2020). "A recent study revealed that the risk of respiratory failure for patients with IL-6 levels of ≥ 80 pg/ml was 22 times higher than for patients with lower IL-6 levels." (PMID 32760408, 2020).
respiratory failure (continued). "Similar to infections of SARS-CoV-1 and MERS-CoV, where cytokine release syndrome (CRS) was found to be the major cause of morbidity, in SARS-CoV-2 infection, elevated IL-6 correlates with severe respiratory failure." (PMID 32992775, 2020). "Results demonstrated that elevated plasma concentrations of IL-6 are strongly associated with the need for mechanical ventilation (p = 1.2 × 10–5) and respiratory failure (p = 1.7 × 10–8)." (PMID 32992775, 2020). "Our aim was to evaluate the levels of activin A, activin B, FS, IL-6 and IL-10 and their association with the severity of respiratory failure in critically ill H1N1 patients." (PMID 24885241, 2014). "IL-6 showed moderate correlations with both mechanical ventilation (ρ = 0.450) and death (ρ = 0.452; both p < 0.001), indicating that cytokine storm features are closely associated with severe respiratory failure and fatal outcomes." (PMID 41463074, 2025). "The association between respiratory failure and higher levels of IL-1ra, IL-6, IL-8, MCP-1, MIP-3α, and MIP-3β persisted, and again MCP-1 was the cytokine with the highest estimate (OR 16.15, CI 4.02–64.86), followed by IL-6 (OR 8.30, CI 2.84–24.23), and IL-8 (OR 3.83, CI 1.78–8.21)." (PMID 38985797, 2024). "Functionally, IL-6 has been associated with increased vascular permeability and interstitial edema that worsens the respiratory situation and may play a role in respiratory failure." (PMID 37834869, 2023). "Although the number of patients was small (n = 36), the results suggest that a larger percentage of decreased serum IL-6 concentrations after admission indicated a lower risk of developing respiratory failure in late admission (ROC curve area = 0.696, p = 0.072)." (PMID 37214473, 2023). "Functionally, IL-6 has been associated with increased vascular permeability and interstitial edema that worsen the respiratory situation and may play a role in respiratory failure." (PMID 37834869, 2023). "Recently, the Severe Covid Prediction Estimate (SCOPE) calculated from circulating concentrations of CRP, DD, ferritin and IL-6 has been validated to stratify the risk of progression to severe respiratory failure or death with a similar predictive accuracy to suPAR." (PMID 36961847, 2023). "In this study, we demonstrated a novel IL-6 detection POC diagnostic device that could detect those at risk of respiratory failure." (PMID 35242747, 2022). "Patients with these underlying diseases may develop respiratory failure even if they have low serum IL-6 levels." (PMID 35242747, 2022). "IL-6 is known to be a major regulator of acute-phase protein synthesis, and IL-6 levels in serum have been reported to strongly correlate with COVID-19 infection and risk of respiratory failure in several studies." (PMID 35336960, 2022). "IL-6 levels are associated with respiratory failure and poor prognosis." (PMID 34177566, 2021). "Patients with the IL-6 above 24 pg/m at initial assessment seems to be at high risk of development of respiratory failure and might benefit from early hospitalization and close follow-up." (PMID 33781216, 2021). "Elevated levels of the pro-inflammatory cytokine IL-6 has been found to be associated with systemic inflammation and hypoxic respiratory failure observed in severe or critical COVID-19 infections, predicting respiratory failure and mortality." (PMID 33298930, 2020). "High plasma IL-8/CXCL8 [median(IQR), 17.6(5.9–27.3) vs 4.3(3.6–9.0) pg/mL, P<0.001) and IL-6 [16.2(7.4–37.7) vs 8.7(5.5–15.0) pg/mL, P = 0.026] concentrations were significantly associated with development of respiratory failure; the same cytokines were also associated with ICU admission/death." (PMID 27434276, 2016). "Finally, levels of IL-6 of >35 pg/mL may indicate a risk of respiratory failure in the context of a COVID-19 infection." (PMID 36983566, 2023). "Finally, IL-6 levels of >35 pg/mL may indicate a risk of respiratory failure in the context of COVID-19 infection." (PMID 38203482, 2023).
respiratory failure (continued). "Elevated CRP levels correlate with unfavorable outcomes, including accelerated disability in MS, IL-6-mediated astrocyte injury in NMOSD, respiratory failure in GBS, and crisis susceptibility in MG." (PMID 41683748, 2026). "Similar results were observed in an Italian study, which confirmed that CT involvement correlates with CRP, IL-6, IL-8, and tumor necrosis factor α (TNF-α) serum levels in severely ill patients with a high risk of acute respiratory failure." (PMID 40428781, 2025). "Serum IL-6 levels have been correlated with the stage of COVID-19 disease, particularly in patients experiencing respiratory failure." (PMID 41009326, 2025). "For example, one study group suggested a cutoff of 70 pg/mL for IL-6 for predicting severity and survival, while another research group proposed 80 pg/mL for predicting respiratory failure." (PMID 39518964, 2024). "Recent studies showed that COVID‐19 patients with elevated levels of HBP, IL‐6, and CRP faced a significantly increased risk of respiratory failure." (PMID 39187469, 2024). "This aberrant signaling pathway contributes to respiratory failure and multiorgan damage, underscoring the critical nature of IL-6 in disease progression." (PMID 39518964, 2024). "An association between elevated interleukin 6 (IL-6) and C-reactive protein (CRP) after this initial period of viral replication was soon correlated with risk of respiratory failure and mechanical ventilation." (PMID 39220656, 2024). "The higher level of IL-6 concentration is closely related to the requirement for ventilatory assistance and the development of respiratory failure." (PMID 37951972, 2023). "A longer hospital stay was associated with the presence of respiratory failure and ICU transfer, and serum levels of IL-6, IL-8, and IL-10 were higher in these patients." (PMID 37969879, 2023). "First, as a pilot study to evaluate the correlation between sequential IL-6 concentrations and respiratory failure, the number of patients was small, with some of the results not reaching statistical significance." (PMID 37214473, 2023). "Interleukin-6 (IL-6) plays a crucial role and has predictive value in CAP; high serum IL-6 concentrations in adults are associated with high respiratory failure and mortality rates." (PMID 37214473, 2023). "This drug is intended only for patients with respiratory failure and highly elevated IL-6 level (according to various sources: more than 75 and 100)." (PMID 37608339, 2023). "IL-6 and TNF are linked with fever and with constitutional symptoms, and increase in capillary permeability, hypotension, and acute respiratory failure." (PMID 36982991, 2023). "In another study, a binary logistic regression, the interleukin-6 level was the most significant predictor of the non-survivor group when compared to age and C-reactive protein, showing that interleukin-6 correlates with respiratory failure." (PMID 37366985, 2023). "In our study, elevated IL-6, IL-8, and IL-10 serum levels were correlated with the presence of respiratory failure." (PMID 37969879, 2023). "IL-6 concentrations tended to decrease more in the non-respiratory failure group compared to the respiratory failure group (p = 0.071)." (PMID 37214473, 2023). "IL-6, a proinflammatory cytokine, drives immune dysregulation and respiratory failure leading to higher mortality." (PMID 36510222, 2022). "Our analysis revealed the elevated expression of the pro-inflammatory cytokine IL-6 in the murine lungs which has been shown to positively correlate with disease progression and respiratory failure." (PMID 36000328, 2022). "This is in agreement with previous studies that showed IL-6 to be a sensitive and specific predictor of disease severity and clinical outcomes such as death and respiratory failure." (PMID 35248063, 2022). "Other studies demonstrated that elevated IL-6 concomitantly with raised CRP were highly expected to indicate respiratory failure." (PMID 35530861, 2022).